EPHB4 (EPH receptor B4)
Diseases named in the same sentence as EPHB4 in open-access papers (continued):
Sharing a sentence is not in itself a finding about the gene and the disease.
cancer (continued). "Additionally, EphB4 knockout cells had increased expression of matrix metallopeptidase 14, pinin, and keratins 7, 8, 16, and 20, genes associated with increased proliferation, EMT, and metastasis across multiple cancer types." (PMID 39091728, 2024). "Therefore, carefully examining the directionality of EphB4-ephrinB2 signaling on cancer cells and on vascular endothelial cells is of paramount importance to differentiate between drivers of tumorigenic effects in the cancer cells and/or the TME." (PMID 35725568, 2022). "However, if for VEGF and EphB4 a solid base of supporting evidence has established their role in angiogenesis and cancer blood vessel formation, in the case of IGF-II, its angiogenic role in the literature has been variably and interchangeably associated with the angiogenic role of IGF-I." (PMID 32033443, 2020). "Therefore, we sought to determine whether the ER stress induced by EPHB4 inhibition is related to ATP depletion in cancer cells." (PMID 31641103, 2019). "Furthermore,EphA2 or EphB4 inhibition could reduce ameboid-type migration of cancer cells andcould stabilize epithelial adherens junctions in various cancer cell lines, assuggested by Fang and Yang." (PMID 21479221, 2011). "However, the role of the EphB4/ephrin-B2 system in other cancer cell types is controversial." (PMID 22194865, 2011). "Therefore, overexpression of EphB4 by cancers can likely provide an angiogenic advantage to them." (PMID 17353927, 2007). "However, there is growing evidence that EphB4 may provide more direct survival cues to cancer cells." (PMID 17353927, 2007). "CLDN1, EphB4, LAT1, FOXM1, HSP105α, ROBO1, and SPARC were identified as potential targets for common cancer antigens for primary CRC." (PMID 40806530, 2025). "In particular, EphB4, CLDN1, and LAT1 are expressed at high frequencies in most cancers, with a few exceptions." (PMID 40076777, 2025). "CLDN1, EphB4, LAT1, HSP105α, and ROBO1 expression slightly decreased or remained unchanged but remained consistently high across both cancer types." (PMID 40806530, 2025). "To determine if EphB4 knockdown in the cancer cell directly affects the CD4 + T cell state, we cocultured control or EphB4 shRNA cancer cells with CD4 + T cells and conducted flow cytometry." (PMID 39489818, 2025). "Representative examples of five common cancer antigens, GPC3, ROBO1, CLDN1, EphB4, and LAT1, expressed on the cell membrane of cancer cells are shown." (PMID 40076777, 2025). "In conclusion, the findings in this study demonstrated that exosomes from SRGN-overexpressing ESCC cells play important roles in cancer progression, with SRGN- induced exosomal M6PR and EphB4 having pro-angiogenic and pro-invasive functions, respectively." (PMID 36632458, 2023). "At Year 2, cancer-related pathways including ERBB signaling and some axonal guidance signaling pathways such as EphB4 signaling were perturbed." (PMID 37513116, 2023). "Interaction of EphB4 with its ligand ephrin B2 plays critical roles in both normal development and cancer progression, and in HNSCC, EphB4 is highly expressed in cancer and stromal cells, with lower expression of ephrin B2." (PMID 36175961, 2022). "The EPHB4 kinase inhibitor, AZ12672857, indeed decreased cancer cell viability, leaving normal cells unharmed." (PMID 33120942, 2020). "The present study identifies EphB4 intracellular last residue, Tyrosine 987, as the specific target of the autocrine IGF-II signal in cancer and it links its phosphorylation status with the protein stability and overall lifespan of EphB4 expression." (PMID 31270394, 2019). "This study identifies WIPF2, EPHB4 and MTHFD2 as novel regulators of vimentin expression by using a high-throughput RNAi screening approach targeting cancer relevant genes." (PMID 23295955, 2013). "CLDN1, EphB4, and LAT1 were expressed only on the cell membrane of cancer cells." (PMID 40076777, 2025).
cancer (continued). "Together, these data suggest that cancer cell EphB4 likely regulates metastasis through non-canonical EMT and Wnt signaling." (PMID 39489818, 2025). "On the other hand, it has been revealed that three antigens—EphB4, CLDN1, and LAT1—are frequently expressed only on the cell membrane of cancer cells in various solid cancers, suggesting that they may be ideal targets for CAR-T cell therapy." (PMID 40076777, 2025). "We analyzed expression levels and intracellular localization of seven common cancer antigens, CLDN1, EphB4, LAT1, FOXM1, HSP105α, ROBO1, and SPARC, and human leukocyte antigen (HLA) class I via immunohistochemical staining of 85 surgical specimens from primaries and liver metastases." (PMID 40806530, 2025). "The data indicate that all cases of primary CRC and CRCLM might be adaptable for CAR-T cell therapy targeting any of the three membrane-type protein cancer antigens, namely CLDN1, EphB4, and LAT1." (PMID 40806530, 2025). "Our mass spectrometry proteomics analysis of EphB4 knockdown in MOC2 cells revealed dysregulation of proteins involved in cell division, which may enhance the intrinsic capacity of cancer cells to metastasize." (PMID 39091728, 2024). "EPHB4 belongs to the receptor tyrosine kinases (RTK) family, with widespread roles in physiological and pathological processes, and frequently upregulated in cancer cells through activation of the PI3K signaling pathway and related to poor prognosis." (PMID 37511951, 2023). "EPO-R and EphB4 are expressed in a wide range of tissues, hematopoietic and nonhematopoietic cancers at the RNA and protein level." (PMID 37543610, 2023). "Indeed, EPORs of cancer cells are located either on the membrane surface or as a soluble intracellular forms, and apart from the classical EPOR, ephrin-type B receptor 4 (EPHB4) as an alternative EPO binding form was identified in malignant cells." (PMID 34299300, 2021). "EPHB4 was concluded to be functionally similar to KSR1 and might be targeted successfully in a cancer-specific manner." (PMID 33120942, 2020). "Unfortunately our cohort did not contain lymph nodes, but other studies report EphB4 to be (over)expressed in positive lymph nodes of various cancers." (PMID 32751634, 2020). "Furthermore, H19 regulated many other cancer-related genes in this network, such as AKT3, CSF1, MET, COL1A1, COL5A1, WWTR1, EPHB4, and TMPRSS3." (PMID 31164794, 2019). "Our findings support that the IGF-II-IGFIR signal does not play a role in the control of EphB4 protein stability in cancer." (PMID 31270394, 2019). "In carcinoma samples the expression of both genes is elevated, with EPHB4 being significantly up-regulated in comparison to benign tissue samples, but expression of both ITGB8 and EPHB4 is much lower than in PIN tissues." (PMID 25886373, 2015). "Membrane proteins, such as CLDN1, EphB4, and LAT1, were highly expressed in primary CRC and liver metastases, suggesting that CAR-T cell therapy targeting these three cancer antigens could be a viable option, particularly in 30% of cases with reduced HLA class I expression on cancer cell membranes." (PMID 40806530, 2025). "EphB4 in cancer cells has paradoxical effects depending on whether or not its cognate ligand EFNB2 is present." (PMID 35565468, 2022). "Therefore, EPHB4 is a promising therapeutic target for the development of novel treatment for various types of cancers." (PMID 35689424, 2022). "Other studies indicate that the regulatory functions of individual C19MC miRNAs in cancer are related to silencing the expression of factors and signaling pathways related to adhesion, migration, differentiation, growth and angiogenesis (Rap1b, ABCG2, DAPK2, ephrins-EphB2 and EphB4, CXCR4)." (PMID 36430313, 2022).
cancer (continued). "In order to test whether EphB4 and the autocrine IGF-II system were part of a common mechanism in cancer, we profiled a number of cancer cell lines for the expression of the IGF-II loop autocrine components combining both known data with experimental validation." (PMID 31270394, 2019). "We have detected inhibitory cis interactions with ephrins in cancer cells not only for EphA3, which had been previously studied in neurons, but also for endogenous EphA2 and EphB4, for which the effects of cis interactions have not been previously investigated." (PMID 24348920, 2013). "To test this hypothesis, we first examined the expression of ephrinB2 and EphB4 in a compartment-specific manner in different murine (Moc2, Ly2, and MEER) and patient-derived xenograft (CUHN013) HNSCC models, with a particular focus on cancer cells and vascular endothelial cells." (PMID 35725568, 2022).
adenocarcinoma (8 papers, 2005 to 2022). A common cancer characterized by the presence of malignant glandular cells. "Of 16 sites with EPHB4 mutations in adenocarcinoma tissues, 12.5% were located in the kinase domain." (PMID 26073592, 2015). "If the PIN is a precursor to adenocarcinoma in this case, this might suggest that increased expression of EphB4 was an early event in the development of this patient's disease." (PMID 16171530, 2005). "One of the patients examined here also showed a comparable level of EphB4 staining in foci of PIN and poorly differentiated adenocarcinoma." (PMID 16171530, 2005). "To validate the overexpression of EphB4 in PDAC and determine its localization, we performed immunohistochemistry on 18 tissue microarrays (TMAs) of treatment naïve PDAC consisting of 346 unique individuals with adenocarcinoma using an anti-EphB4 antibody." (PMID 34298619, 2021).
infection (4 papers, 2015 to 2024). The state of being infected such as from the introduction of a foreign agent such as serum, vaccine, antigenic substance or organism. "The expression of these receptors, as well as EphB4, were suppressed by miR-181 overexpression, suggesting that simultaneous inhibition of several Ephs by the miRNA contributes to enhanced infection and fusion." (PMID 27783670, 2016). "To test whether reduced protein levels of EPHB4, ERBB2, FGFR2, or IGF1R impacted infection, we infected control and knockdown lines with DENV2 MON601 for 24 h." (PMID 38585651, 2024). "In contrast to EphA2, PDGFRβ is downregulated during Ctr infection and no significant changes were observed for PDI or EphB4 expression, suggesting that EphA2 is specifically upregulated and activated during Ctr infection." (PMID 25906164, 2015).
vascular disorder (4 papers, 2021 to 2024). A general term used to describe any disease affecting blood vessels]. "Loss of EPHB4 or RASA1 function in EC results in dysregulated Ras-MAPK signaling that drives the development of vascular abnormalities in CM–AVM and other vascular disorders." (PMID 37259315, 2023). "Use of NGS-based gene panels including not only ENG, ACVRL1 and MADH4 but also RASA1 and EPHB4 genes, which are associated with the HHT-like syndrome accelerates the diagnosis of these hereditary vascular disorders." (PMID 33807613, 2021). "‘HHT gene-negative’ families receiving a clinical positive test result included the original HHT3 family, and a family diagnosed with a related vasculopathy (capillary malformation (CM)-AVM213), due to a heterozygous variant in EPHB4 that lies on the same chromosome as the HHT4 locus." (PMID 37586837, 2024). "Alternatively, because loss of RASA1 or EPHB4 function is initially expected to be localized to individual EC in human vascular disorders, it is possible that adjacent RASA1- or EPHB4-sufficient EC can rescue RASA1- or EPHB4- null EC from apoptosis through provision of collagen IV in trans." (PMID 37259315, 2023).
hematologic cancer (1 paper, 2022). "To identify an EPHB4 inhibitor with a potential of rapid translation into clinic, we screened a pool of clinically approved compounds using hematologic cancer cells expressing different levels of EPHB4." (PMID 35689424, 2022).
prostate (1 paper, 2011). "Such nanoparticles, filled with an infrared fluorescent dye and labeled with Indium-111, were successfully used to visualize EphB4-expressing prostate xenograft tumors in mice by both optical imaging and single photon emission computed tomography (SPECT)." (PMID 22194865, 2011).
retinopathy (1 paper, 2013). "Furthermore, EphrinB2/EphB4 expression is present in the retinal neovascularization model of high oxygen-induced retinopathy of mouse prematurity and the laser-induced CNV model, indicating that EphrinB2/EphB4 plays a role in retinal neovascularization and CNV formation." (PMID 23596494, 2013).
EPHB4 also shares sentences with these, for which no sentence is quoted: hereditary hemorrhagic telangiectasia (4 papers); ischemic stroke (3); leukemia (3); atrial septal defect (2); bone disorder (2); brain tumors (2); cardiac hypertrophy (2); Ewing sarcoma (2); fibrosarcoma (2); hydrops (2); invasive breast carcinoma (2); Pleural effusion (2); acute myelogenous leukemia (1); adenoma (1); alveolar rhabdomyosarcoma (1); Anxiety (1); Arrhythmia (1); autosomal dominant disease (1); Behçet disease (1); benign ovarian tumour (1); benign prostate tumour (1); biliary tract cancer (1); cardiomyopathy (1); central conduction lymphatic anomaly (1); cerebral cavernous malformation (1); Cerebral ischemia (1); cervical intraepithelial neoplasia (1); chordoma (1); Chylothorax (1); clear cell carcinoma (1).
A further 46 diseases each share a sentence with EPHB4 in 1 paper.